RNY3P11 (RNY3 pseudogene 11)
Gene: Miscellaneous RNA gene on chromosome 6 (109,305,494 to 109,305,595, forward strand). Ensembl gene ENSG00000201023.
Homologues: Orthologues: chimpanzee Y_RNA (97% identical), macaque Y_RNA (96% identical). Paralogues in human: RNY3P1 (91% identical), Y_RNA (91% identical), RNY3 (90% identical), Y_RNA (90% identical), Y_RNA (89% identical), Y_RNA (88% identical), Y_RNA (87% identical), Y_RNA (86% identical), Y_RNA (85% identical), RNY3P14 (84% identical), RNY3P16 (84% identical), Y_RNA (84% identical), and 94 more.